ENSG00000300257 (novel transcript)
Gene: Long non-coding RNA gene on chromosome 6 (28,212,613 to 28,219,421, forward strand). Ensembl gene ENSG00000300257.
Gene Ontology:
Molecular function: triplet codon-amino acid adaptor activity
Biological process: translation